RN7SL390P (RNA, 7SL, cytoplasmic 390, pseudogene)
Gene: Miscellaneous RNA gene on chromosome 12 (54,255,627 to 54,255,910, reverse strand). Ensembl gene ENSG00000241785.
Homologues: Orthologues: chimpanzee Metazoa_SRP (98% identical), macaque Metazoa_SRP (92% identical). Paralogues in human: RN7SL1 (82% identical), RN7SL2 (82% identical), RN7SL3 (81% identical), RN7SL597P (79% identical), RN7SL45P (79% identical), RN7SL655P (79% identical), RN7SL448P (79% identical), RN7SL507P (79% identical), RN7SL543P (79% identical), RN7SL125P (78% identical), RN7SL444P (78% identical), RN7SL827P (78% identical), and 702 more.